AMH (anti-Mullerian hormone)
Diseases named in the same sentence as AMH in open-access papers (continued):
Sharing a sentence is not in itself a finding about the gene and the disease.
breast carcinoma (continued). "The first prospective study in premenopausal women reported a strong association of AMH (OR = 9.8, 95% CI: 3.3-28.9) with breast cancer before the diagnosis, although a weaker association was observed in breast cancer patients who were not using oral contraceptive during blood collection." (PMID 33718762, 2021). "A question that still needs to be investigated is whether the AMH level before any anticancer treatment is impacted by cancer itself or abnormal AMH level is one of the risk factors of breast cancer?" (PMID 33718762, 2021). "From an oncological perspective, as BRCA1/2 protein defects sensitize breast tumor cells to various chemotherapeutic agents that induce DNA lesions, we investigated whether there was an association between tumor response to NAC and changes in AMH concentrations during NAC in breast cancer patients." (PMID 40220108, 2025). "Finally, various individual susceptibilities to CT may also impact longitudinal AMH levels change in young breast cancer women." (PMID 40220108, 2025). "From a clinical perspective, these results suggest that, in gBRCApv, monitoring AMH changes during NAC (from baseline to Mid-CT) using a hypersensitive assay could provide early information on the response of BRCA-deficient breast cancer cells to the anthracycline regimen." (PMID 40220108, 2025). "Based on laboratory evidence in cell-line and mouse models, an inverse association between AMH level and breast tumor development has been illustrated, and it seems that AMH has a protective effect against breast cancer and can suppress the growth of mammary tumors." (PMID 33718762, 2021). "METHODS: Ovarian tissue was obtained from five women with a mean age of 27 years (20–33 years), different tumor entities (breast carcinoma [n = 2], B-cell lymphoma, melanoma, medulloblastoma) and AMH levels above 2 ng/mL (4.28 ng/mL ± 1.89)." (PMID 41840688, 2026). "Our results contribute to the growing body of evidence that AMH is a valuable biomarker for ovarian reserve, not only in the context of fertility but also in other malignancies such as breast cancer." (PMID 40848466, 2025). "To achieve this, we analyzed AMH slopes in breast cancer patients with a gBRCApv and WT using a hypersensitive AMH assay." (PMID 40220108, 2025). "In conclusion, our study demonstrates that pretreatment AMH is a strong predictor of ovarian function resumption following chemotherapy in premenopausal breast cancer patients." (PMID 40848466, 2025). "Pretreatment AMH is a valuable tool for predicting ovarian function resumption after chemotherapy in breast cancer patients, so that a GnRH agonist can be recommended appropriately." (PMID 40848466, 2025). "Given that defects in BRCA1/2 sensitize breast cancer cells to several DNA-damaging agents, we also investigated the correlation between AMH decline during NAC and tumor response to treatment in both gBRCApv and WT patients." (PMID 40220108, 2025). "As the first study, investigating the protective effect of vitamin D on ovarian reserve of the breast cancer patients, there was a slightly higher mean AMH rise in patients receiving 1000 IU calcitriol." (PMID 38925607, 2024). "Breast cancer cell growth has also been shown to be inhibited by AMH in vitro and in vivo in mice by interfering with cell cycle progression and the induction of apoptosis." (PMID 39230026, 2024). "This study is the first study evaluates the protective effect of vitamin D on the OR of breast cancer patients undergoing chemotherapy by comparing AMH levels before and six months after chemotherapy with vitamin D supplements." (PMID 38925607, 2024). "The AMH level is a potent predictor of ovarian function after chemotherapy in premenopausal breast cancer patients older than 35 years, either for ovarian function injury or ovarian function recovery." (PMID 37410375, 2023). "Research on AMH and its receptors in recent years has led to a better understanding of its role in breast cancer." (PMID 37410375, 2023).
breast carcinoma (continued). "In the first study in 2013, there were 55 and 46 women evaluable at 12 and 24 months after the breast cancer diagnosis, respectively, and the authors found an AUC for pretreatment AMH of 0.90 (95% CI 0.82–0.97), and for age, 0.88 (95% CI 0.78–0.97)." (PMID 37698031, 2023). "We found three studies that explored the predictors of amenorrhea such as age, pre‐ and post‐treatment AMH as well as tamoxifen treatment after breast cancer chemotherapy." (PMID 37698031, 2023). "Many scientists have shifted their focus to laboratory studies with the goal of determining the relationship between AMH and breast cancer." (PMID 37410375, 2023). "This review abstracts the complex relationships among AMH, the gonadal axis, and breast cancer, with the goal of providing novel ideas for the diagnosis and treatment of breast cancer." (PMID 37410375, 2023). "This explains the effect of endocrine therapy on anti-breast cancer cells from the perspective of AMH." (PMID 37410375, 2023). "Since AMHRII is expressed in breast cancer cells and triggers apoptosis, AMH/AMHRII will arouse innovation in the occurrence, typing, and targeted therapy of breast cancer." (PMID 37410375, 2023). "In women with breast cancer, AMH levels before the treatment have recently been shown to be a useful predictor of the post-chemotherapy loss of ovarian function, in addition to age, which is the only other established individual predictor." (PMID 35626104, 2022). "When comparing AMH of BRCA2m breast cancer patients to wild-type breast cancer patients, seven studies were included." (PMID 34627117, 2021). "According to IHC of breast cancer patients, AMH level was higher in ER-positive (p = 0.07) and Her2-negative tumors (p = 0.03)." (PMID 33718762, 2021). "The serum levels of AMH in young women with early breast cancer prior to any treatment was compared to healthy women in the present study considering confounding factors." (PMID 33718762, 2021). "In conclusion, we found the lower and higher AMH level categories are more prevalent in young breast cancer patients who were in premenopausal status and didn't receive any cytotoxic treatment." (PMID 33718762, 2021). "The results of in vivo and human studies showed inconsistency with respect to the relation between AMH and breast cancer." (PMID 33718762, 2021). "It seems that further evaluation of AMH level in subtypes of breast cancer is needed for appropriate fertility preservation counseling." (PMID 33718762, 2021). "Some of them assert that a lower AMH is associated with a higher rate of breast cancers, while others have shown a positive relationship between AMH level and breast cancer." (PMID 33718762, 2021). "Nowadays, AMH has been shown, in young premenopausal women with breast cancer, to be the most sensitive marker for predicting ovarian function recovery and premature ovarian insufficiency." (PMID 34376160, 2021). "When comparing AMH of BRCA1m breast cancer patients to wild type breast cancer patients, nine studies were included [5,6,10,]." (PMID 34627117, 2021). "Blumenfeld has discussed the recent study by Ge and colleagues which has found that the breast cancer has a positive relation with AMH level." (PMID 33718762, 2021). "When comparing AMH of BRCA1m and BRCA2m breast cancer patients under age 42 to wild type breast cancer patients, two studies were included." (PMID 34627117, 2021). "Based on our knowledge, this is the first evaluation of the AMH level in young Iranian breast cancer patients." (PMID 33718762, 2021). "In the future, we need more follow up time to prove that GnRHa can increase DFS for breast cancer patients and with more events, we can possibly further define the clinical use of GnRHa according to AMH levels during chemotherapy." (PMID 31413747, 2019).
breast carcinoma (continued). "In breast cancer and prostate cancer, AMH activates the pathway of NFκB (nuclear factor kappa-light-chain-enhancer of activated B cells), which induces the IEX gene (immediate early gene), encoding the protein regulator of the cell cycle." (PMID 30884769, 2019). "In accordance with a GnRHa-mediated decrease in serum levels of AMH, a reduction in the levels of AMH were observed following GnRHa treatment in premenopausal women with breast cancer." (PMID 26126720, 2015). "However, it is important to note that the relationship between AMH and breast cancer is complex, as the disease itself can also influence AMH levels." (PMID 40848466, 2025). "The strength of this study lies in its first-time investigation of AMH level changes in BRCA1/2-mutated versus non-mutated young breast cancer patients, both at baseline and during NAC, alongside tumor size changes." (PMID 40220108, 2025). "However, the impact of intrinsic AMH expression in breast cancer cells on their tumoral biology remains unexplored 48-50." (PMID 38911383, 2024). "Moreover, there was a closer connection between AMH and breast cancer for women who were diagnosed with breast cancer at an older age (more than 45 years old) than for those who were diagnosed at a younger age (less than 45 years old)." (PMID 37410375, 2023). "Blumenfeld has mentioned that the positive relation of breast cancer with AMH level may be due to a higher prevalence of PCOS patients in the high AMH-level group." (PMID 33718762, 2021). "Presence of a deleterious BRCA germline mutation did not affect AMH level in breast cancer patients undergoing chemotherapy and endocrine therapy." (PMID 34627117, 2021). "It seems that AMH assessment in other subtypes of breast cancer is necessary." (PMID 33718762, 2021). "However, the lower and higher AMH level categories are more prevalent in breast cancer compared to the control." (PMID 33718762, 2021). "Our results suggest that abnormal AMH level is more frequent in young breast cancer patients." (PMID 33718762, 2021). "Another epidemiologic study by Su and co-workers on very young breast cancer patients (28-44 yr) found a significantly lower AMH in breast cancer patients in univariate analysis, and AMH levels that were more frequently below the detection rates in breast cancer patients than that of controls." (PMID 33718762, 2021). "Although we could not determine the effect of chemotherapy with only four patients, we can extract oocytes in accordance with the AMH levels in similar patients who undergo treatment for breast cancer." (PMID 25464895, 2015). "Therefore, we conclude that the number of oocytes extracted from cryopreserved ovarian tissue is well-correlated with the breast cancer patients’ AMH levels and age at the time of surgery." (PMID 25464895, 2015). "Moreover, in vitro studies have shown that AMH inhibits the growth of ovarian, endometrial and breast cancer cell lines." (PMID 24312319, 2013). "Moreover, AMH may play an important role in the occurrence, treatment and prognosis of breast cancer, which needs further research." (PMID 37410375, 2023). "With regard to our hypothesis, the reduction in circulating estrogen levels caused by endocrine therapy may decrease the inhibition of AMHRII expression on the surface of breast cancer cells by estrogen; thus, more AMH can bind to its receptor and induce tumor cell apoptosis." (PMID 37410375, 2023). "Consequently, it is worth investigating whether AMH could be a predictor for the occurrence of breast cancer." (PMID 37410375, 2023). "This study supported the hypothesis of the relationship between AMH levels and breast cancer." (PMID 33718762, 2021). "We have previously reported that chemotherapy-induced ovarian toxicity may derive from acute vascular insult, demonstrated by decreased ovarian blood flow and diminished post-treatment anti-Müllerian hormone (AMH) levels in a cohort of young breast cancer patients treated with chemotherapy." (PMID 33297351, 2020).
breast carcinoma (continued). "AMH causes a similar response in the estrogen-negative line of breast cancer (MDA-MB-231)." (PMID 30884769, 2019). "Also, it produces high levels of anti-Mullerian hormone (AMH) which could suggest PCOS is the original factor responsible for the increased breast cancer risk occurring in women with high levels of (AMH), not the increase in the hormone itself." (PMID 37809638, 2023). "The binding of AMH and AMHRII on the surface of breast cancer cells is also attenuated, thus blocking an apoptotic pathway of breast cancer cells to some extent." (PMID 37410375, 2023). "In WT patients, any DNA repair deficit (if present) would only affect breast cancer cells due to somatic BRCA1/2 mutations, explaining the lack of correlation between AMH decrease and tumor size reduction." (PMID 40220108, 2025). "Nevertheless, AMH treatment was shown not to interfere with the cytotoxic actions of cyclophosphamide on breast cancer cells or an in vivo model of human leukaemia and AMH has been shown not to affect tumour growth." (PMID 38070496, 2024). "The results from a clinical study that we conducted indicated that the AMH levels of premenopausal breast cancer patients over 35 years old were reduced after CTX-based chemotherapy, and the level of serum AMH before chemotherapy can be used as a predictor of menstrual recovery after chemotherapy." (PMID 37410375, 2023). "We believe that AMH levels in humans are not sufficient to resist the effects of estrogen on breast cancer cells." (PMID 37410375, 2023). "Since AMHRII is expressed in breast cancer cells and triggers apoptosis, AMH/AMHRII may play an important role in the occurrence, treatment, and prognosis of breast cancer, which needs further research." (PMID 37410375, 2023). "When comparing AMH of women carrying BRCA1-2 pathogenic variants with and without breast cancer to wild type women with and without breast cancer, five studies were included." (PMID 34627117, 2021). "Our finding is in line with previous studies showing that pretreatment AMH was a predictor of chemotherapy-related amenorrhea in breast cancer patients both without ovarian protection as well as those with ovarian protection using GnRH agonists." (PMID 32656076, 2020). "But this conclusion has been strongly disputed by Blumenfeld, who believes that the association of high AMH and breast cancer may be due to a higher prevalence of PCOS in the high AMH group and not due to high AMH, per se." (PMID 37410375, 2023). "In addition, AMH levels in prospective epidemiological studies were not obtained at the time of breast cancer diagnosis." (PMID 37410375, 2023). "Nevertheless, another study showed that even though the fertility of Tamoxifen-treated patients with breast cancer was lower than that of those who did not receive treatment, there was a higher AMH level in Tamoxifen-treated women, suggesting no reduction in ovarian reserve (OR)." (PMID 34376160, 2021). "The first limitation of the current study is that since the AMH level was evaluated after a breast cancer diagnosis, it might not reflect the AMH level before cancer development." (PMID 33718762, 2021). "Despite a minimal rise in the AMH level after six months of chemotherapy, the study could not demonstrate any protective effect of vitamin D on patients' ovarian reserve undergoing chemotherapy for breast cancer." (PMID 38925607, 2024). "However, for breast cancer patients in general, AMH levels do not appear to be reduced." (PMID 38400669, 2024).
premature ovarian failure (30 papers, 2012 to 2026). "The present study showed that BRCA 1 patients have a higher risk of premature ovarian failure confirmed by a diminished ovarian reserve, sustained by a lower AMH (an important ovarian reserve serum marker) and a lower mature oocytes’yield." (PMID 31872386, 2020). "AMH level shows a decreasing trend with age, gradually decreasing after reaching its peak during puberty and approaching zero after menopause, which can predict the risk of fertility decline and premature ovarian failure." (PMID 40597965, 2025). "The AMH level shows a decreasing trend with age, gradually decreasing after reaching its peak during puberty and approaching zero after menopause, which can predict the risk of fertility decline and premature ovarian failure." (PMID 40597965, 2025). "The trend of FSH, AMH, and E2 hormone serum levels over the one-monthtreatment period with very small stem cells from peripheral blood inpatients with premature ovarian failure." (PMID 38640352, 2024). "Our cohort also included four women who had AMH values <0.5 ng/ml, which is indicative of fertility impairment/potential premature ovarian failure; yet, oocytes were successfully collected following cancer treatment, although no pregnancies were achieved." (PMID 38806697, 2024). "Based on both paraclinical values performed at all three visits, 29 patients, 76.32%, were diagnosed with premature ovarian failure, with a recorded AMH serum value <0.01 ng/mL." (PMID 38255651, 2023). "Knockout AMH accelerates primordial follicle activation and leads to premature ovarian failure in mice." (PMID 36611886, 2022). "She started spontaneous puberty; however, initial biochemical evaluation revealed hypergonadotropic hypogonadism with undetectable anti-Mullerian hormone (AMH) consistent with low ovarian reserve and premature ovarian failure." (PMID 34987878, 2021). "After treatment, however, AMH concentrations showed very little recovery (median 0.11 pmol/L at 1 year), and patients aged over 35 years were more likely to experience premature ovarian failure (POF)." (PMID 34207634, 2021). "In patients with premature ovarian failure, AMH is undetectable or greatly reduced depending on the number of antral follicles in the ovaries." (PMID 33763463, 2021). "Primary gonadal dysfunction (i.e., primary hypogonadism) in women was identified in four out of 9 CVID patients (aged≤40 years) that had premature ovarian failure based on low AMH, low estrogen and high LH and FSH levels." (PMID 31543881, 2019). "AMH has been reported to be a promising marker for premature ovarian failure in both healthy women and those with Turner syndrome." (PMID 24406076, 2013). "Our study found that CP treatment decreases AMH’s level and reduces AMH’s inhibitory effect on primordial follicle recruitment, which may lead to overactivation of the primordial follicular reserve and premature ovarian failure." (PMID 36555999, 2022). "In addition, it has been reported recently that Müllerian inhibiting substance (or anti-Müllerian hormone/AMH) can prevent chemotherapy-induced primary ovarian insufficiency by blocking the activation of primordial follicles in C57BL/6 N mice." (PMID 30368246, 2018). "In addition, serum AMH levels in patients with primary ovarian insufficiency (POI) or premature ovarian failure (POF) are extremely low or undetectable." (PMID 27414805, 2016). "In this case–control study, which comprised 169 women with primary ovarian failure and 209 healthy women, the authors monitored follicle-stimulating hormone (FSH), luteinizing hormone (LH), anti-Mullerian hormone (AMH), and estradiol." (PMID 36278024, 2022). "AMH value showed an extremely low, even undetectable level in POF (premature ovarian failure) patients." (PMID 28607932, 2017). "The authors reported lower values of AMH and AFC in patients with pSS, suggesting that this result may represent an early sign of premature ovarian failure." (PMID 39576415, 2025).